CXCL12 (C-X-C motif chemokine ligand 12)
Diseases named in the same sentence as CXCL12 in open-access papers (continued):
Sharing a sentence is not in itself a finding about the gene and the disease.
tumor (continued). "It influences the migration and infiltration of immune cells into tumor tissues by modulating chemokines (e.g., CXCL12) and adhesion molecules (e.g., ICAM-1), and affects immune cell activation and anti-tumor responses by regulating the expression and function of immune cell surface receptors." (PMID 40181983, 2025). "Moreover, AMD3100 is receiving interest as an anti-cancer agent that disrupts the CXCR4/CXCL12 chemokine receptor interaction between neoplastic cells and their microenvironment in tumor progression and metastasis." (PMID 40142155, 2025). "In comparison with primary fibroblasts, metastatic fibroblasts express higher levels of soluble factors, including IL‐6, and CXCL12, suggesting the potential of metastatic fibroblasts to produce secreted factor to create a favourable microenvironment for tumour cell invasion." (PMID 38158643, 2024). "Furthermore, two distinct studies carried out in breast and colorectal cancer samples showed that CAF secretion of CXCL12 recruited monocytes to the tumor area and further induced their differentiation into M2-like macrophages." (PMID 39596815, 2024). "In addition, an important step in the generation of an immunosuppressive tumor microenvironment is the increased expression of the chemokine CXCL12, which has also been observed in the durvalumab window." (PMID 39566464, 2024). "GAMs can be activated by tumor-derived CXCL12, which is negatively regulated by CXCR7." (PMID 38898023, 2024). "Moreover, the correlation between positive CXCL12 expression and nodal involvement, advanced tumor stage, and lymphatic invasion was evident." (PMID 38673838, 2024). "Tumor-associated fibroblasts at the primary tumor site can secrete lymphangiogenic factors like VEGF-C, COX-2, HIF1 alpha chemokines like CCL21, CXCL12, which affect lymphatic endothelial cell permeability, adhesion molecule expression, migration to form nascent capillaries, and ECM remodeling." (PMID 38473419, 2024). "According to a recent study, tumor growth correlated inversely with CXCL12 suggesting that local CXCL12 may impair the primary tumor cell response to the ligand gradient that may contribute to driving the tumor progression." (PMID 38571632, 2024). "The CXCR4/CXCL12 complex mediates tumor growth and metastasis." (PMID 38893721, 2024). "Notably, the BH-gel releases a controlled amount of CXCL12, acting as a “bait” to attract circulating tumor cells to the gel." (PMID 39771496, 2024). "Moreover, C-X-C-type chemokines including CXCL8 (IL-8), CXCL2, and CXCL12 secreted by CAFs are also involved in tumor proliferation by promoting angiogenesis and metastasis (CXCL8 & CXCL12) and increasing PD-L1 expression (CXCL2)." (PMID 38539448, 2024). "CXCL12 expression is higher in healthy tissue (C-MSCs) than tumor tissue (T-MSCs)." (PMID 39075612, 2024). "C-X-C motif chemokine 12 (CXCL12, also known as stromal cell-derived factor 1, SDF-1) and its receptor, C-X-C chemokine receptor type 4 (CXCR4), play an important role in angiogenesis and are associated with tumor progression." (PMID 39201522, 2024). "Additionally, we observed predominant PD-L1 expression on iCAFs, similar to IGF2 and CXCL12, suggesting the pivotal role of iCAFs in tumor immunosuppression." (PMID 39545420, 2024). "We found that both CD8+ T cells and NK cells are abundant in the CXCL12+ tumor area." (PMID 38182756, 2024). "In addition, chemokine CXCL12 induced by hypoxia-induced factors (e.g., HIF-1α) also has a potent angiogenic action when linked to its CXCR4 receptor, highly expressed in tumor vessels, triggering an increase in blood vessel formation." (PMID 39769501, 2024). "CXCL12, secreted by cancer-associated fibroblasts (CAFs), activates the STAT3 pathway, inducing the generation and activation of myeloid-derived suppressor cells, resulting in tumor immune escape and further promoting tumor development." (PMID 38920657, 2024).
tumor (continued). "Notably, QRHX inhibits inflammation and the CXCL12/CXCR4/JAK2/STAT3 signaling pathway, thereby modulating tumor-associated macrophages in murine models and suppressing tumor growth." (PMID 38920657, 2024). "Following the release from the bone marrow, monocytes enter the circulation and are subsequently recruited in the TME by various chemokines (such as M-CSF, CCL2, CCL5, CXCL12, and VEGF) secreted by tumor cells, and then differentiate into tumor associated macrophages (TAMs)." (PMID 39606239, 2024). "Furthermore, in the stromal fibroblasts, the BAG3 targeting strategy effectively lowered tumor cell survival by modulating CXCL12 levels while nurturing an unfavorable cytokine environment." (PMID 39198407, 2024). "As such, MDMX expression in tumor cells may be upregulated in the primary tumor microenvironment by CXCL12 expression." (PMID 39766093, 2024). "CXCL12 negatively correlated with tumor size, this may explain that larger tumors have a worse prognosis." (PMID 38571632, 2024). "Consequently, this downregulates the expression of various mediators of pathological angiogenesis that support tumor survival and proliferation, such as chemokine CXCL12." (PMID 39769501, 2024). "Therefore, migration toward target cells is very important, and this process is regulated and guided by chemokines such as CXCL12, CXCL10, and CCL2, produced by tumor cells, tumor-associated macrophages, and fibroblasts." (PMID 39796680, 2024). "Activated STAT3, by upregulating CXCL12, promotes tumor cell migration." (PMID 38920657, 2024). "Previous studies have demonstrated that CXCL12 can be produced by tumor cells of HCC and ICC." (PMID 38767772, 2024). "Moreover, in vitro experiments conducted with rat and human pituitary tumor cells have provided evidence that CXCL12 stimulates tumor proliferation, DNA synthesis, and GH secretion." (PMID 38716256, 2024). "Notably, tumor cells positive for CXCR4 migrate along the CXCL12 concentration gradient to distant organs exhibiting high CXCL12 expression, thereby facilitating tumor metastasis." (PMID 38920657, 2024). "In order to determine whether, in the tumor microenvironment, tumor cells could be also source of CXCL12, we examined the mRNA and protein expression of CXCL12 in the three cell lines analyzed." (PMID 38803493, 2024). "Tumor-associated DCs (TADCs) can release several growth factors and other molecules, including TGF-β, granulocyte-macrophage colony-stimulating factor (GM-CSF), CXCL12, and TNFα, which are all proangiogenic factors." (PMID 39404428, 2024). "CXCL12high iCAF was also associated in tumor growth by FGF1/7/10 and CXCL12 interactions." (PMID 38892065, 2024). "In addition to CXCL12, the interplay between CAFs and tumor cells involves a complex network of signaling molecules." (PMID 39070795, 2024). "The disruption of CXCR4/CXCL12 signaling can enhance the efficacy of chemotherapy and immunotherapy by blunting the migration and metastasis of tumor cells and remodeling of the immunosuppressive tumor microenvironment (TME)." (PMID 38587644, 2024). "Additionally, IL-6, TNF-α, CXCL12, and leptin are considered to significantly promote tumor cell migration and proliferation, as well as inhibit apoptosis and activate autophagy, facilitating the development of tumor bone metastasis." (PMID 38571500, 2024). "In addition, CAFs can promote tumor angiogenesis by recruiting endothelial progenitor cells via CXCL12/CXCR4 signaling pathway." (PMID 38254110, 2024). "Tumor cells release soluble factors that activate or modify monocytes in the TME to promote the polarization of Tc17 cells; IL-17 derived from Tc17 cells induces tumor cells to produce the chemokine CXCL12, thereby recruiting MDSCs to inhibit cytotoxic CD8+ T cells." (PMID 39676857, 2024).
tumor (continued). "This suggests that the TNFR2/CXCR4/CXCL-12 cascade may have a significant impact on the recruitment of immunosuppressive cells, the initiation of cancer, and the proliferation of tumor cells, thereby supporting the development of BC." (PMID 39609700, 2024). "Together, our findings indicate that the reduced recruitment of DCs into the primary tumor sites of LNM-ICC could be partially explained by a defective production of the chemokine CXCL12." (PMID 38926350, 2024). "Therefore, we decided to assess total and cell-type specific CXCL12 protein expression in pre-treatment tumor samples obtained from GLORIA patients (n = 10) in a posthoc translational analysis." (PMID 38806504, 2024). "Furthermore, TREM2+ Macrophages attracted exhausted CD8+ T cells through chemotaxis facilitated by CXCL12, thereby accelerating T cell exhaustion in tumor tissues." (PMID 38948071, 2024). "In HCC, CAF-derived CXCL12 could upregulate plasminogen activator inhibitor 1 in macrophages, eventually promoting tumour cell proliferation, migration and EMT." (PMID 38303024, 2024). "CXCL11 or CXCL12 can alternatively bind CXCR7 which promotes tumor development." (PMID 38786066, 2024). "However, CXCL12 (stromal cell-derived factor 1) promotes tumor cell survival by inhibiting apoptosis, so CXCL12 downregulation would not support tumor progression." (PMID 39200696, 2024). "CXCL12 is a chemokine with diverse effects in tumor biology." (PMID 39545420, 2024). "Our study shows that, in addition to its function on immune cells, the CXCL12/HMGB1 heterocomplex fine tune modulates CXCL12 activity on tumor cells, and suggests disruption of the complex as a novel therapeutic strategy for inhibiting cancer cell migration and invasion." (PMID 38803493, 2024). "TrxR inhibition might additionally promote oxidation of HMGB1, and the subsequent inhibition of the CXCL12/HMGB1 heterocomplex formation in the tumor microenvironment." (PMID 38803493, 2024). "Interestingly, in our study, we found that hydrogen treatment actually alleviated ROS in CAFs and down‐regulated a key ROS‐induced gene, Nos2, and down‐stream pro‐tumor factors such as Mmp2, Cxcl1, and Cxcl12." (PMID 38757665, 2024). "Until that time, the CXCL12/CXCR4/MDM2/MDMX axis in tumor metastasis is speculative since only the role of in vitro cell migration has been assessed in the current manuscript." (PMID 39766093, 2024). "The CXCL12/CXCR4 axis plays a role in the migration of ASCs towards the tumor site." (PMID 39519109, 2024). "The populations of immunosuppressive cells found in immunologically “cold” tumors promote a tolerogenic environment via the release of cytokines and molecules (e.g., IL-10, TGF-β, indoleamine 2,3-dioxygenase (IDO), and CXCL12) inhibiting tumor cell clearance by immune effectors." (PMID 38339258, 2024). "We observed that CXCL12 expressed in α‐SMA positive cells in the tumour tissues of Rip1‐Tag2." (PMID 38766687, 2024). "Several studies have shown that CAFs promote tumor progression via releasing CXCL12." (PMID 39759028, 2024). "Moreover, an abundance of research has also substantiated that the activated STAT3 signaling pathway can promote the secretion of CXCL12 in both stromal cells and tumor cells." (PMID 38920657, 2024). "Blocking CXCR4 impaired the anti‐tumor effect of CXCL12 in a mouse model." (PMID 39422063, 2024). "Results showed the correlation between CXCL12 and differentiation grade, CEA and TTF-1 protein expression, CD44v6 was associated with tumor stage, chromogranin expression whereas HIF1A and KRT7 were significantly associated with CEA protein expression in the metastatic tissues." (PMID 38877052, 2024). "Fibroblast activation protein (FAP) targeted RPT could deliver radiation dose to CAFs, not only killing CAFs and adjacent TNBC tumor cells, but also reducing the secretion of CXCL12 by CAFs." (PMID 38587644, 2024).
tumor (continued). "We found that in the tissue cohort CXCL12 expression was strongly correlated with differentiation, CEA & TTF-1 protein expression, CD44v6 was associated with tumor stage and chromogranin protein expression and HIF1A & KRT7 showed positive correlation with CEA expression alone." (PMID 38877052, 2024). "However, our study not only confirmed the effects of CXCL12 on tumor cell promotion and metathesis, but also showed the potential value of CXCL12 in tumor treatment." (PMID 38714987, 2024). "Interestingly, CXCL12 transcription is induced in stromal cells via a co-culture with tumor cells as part of the dialogue that exists between the two cell types." (PMID 38139452, 2023). "Notably, CXCL12 is known to promote tube formation and is a potential novel target for tumour angiogenesis." (PMID 37730641, 2023). "In this study, we explored whether CXCL12 tumor expression or the CXCL12 + TICs infiltration predicts chemosensitivity and impacts survival." (PMID 37966614, 2023). "Differentially assessed expression patterns of CXCL12, inadequate analysis of CXCL12 in relation to its receptor, and the inaccurate source of CXCL12 within the tumor may explain the results obtained in our study which differ to existing literature." (PMID 37966614, 2023). "Also increased was CXCL-12, which was shown to promote tumour progression through various mechanisms including metastasis and chemoresistance." (PMID 37938546, 2023). "The expression of CXCR4/CXCL12 was reported to be increased due to the hypoxic tumor environment." (PMID 37484803, 2023). "CXCR4-expressing MM cells promote tumor growth, survival, drug resistance, migration, and homing by transmitting positive signals through interactions with the C-X-C motif chemokine ligand 12 (CXCL12) expressed on BM stromal cells." (PMID 37629558, 2023). "However, another study showed the tumor-suppressive role of CXCL12 in PDAC using the gene-silencing model." (PMID 37488598, 2023). "EPCs may be recruited from bone marrow mobilized by vascular endothelial growth factor A (VEGFA) or C-X-C motif chemokine 12 (CXCL12) released by tumor-infiltrating myeloid cells or cancer cells." (PMID 38148844, 2023). "Overall, we summarized that RB could repress autophagy to block the CXCL12 secretion in CAFs and weaken the CXCL12-mediated tumor promotion of EC." (PMID 37029408, 2023). "Just to cite a few examples, it has been reported that CXCL12, highly expressed in tumor-associated LVs but not in normal ones, promotes the dissemination of CXCR4-expressing cancer cells toward distant organs that highly express CXCL12." (PMID 38068914, 2023). "The results summarized above suggest that CXCL12 is expressed in both tumor and stromal cells within OSCC tissues and that its expression is inversely associated with the clinical aggressiveness of the tumor." (PMID 36300800, 2023). "The expression of CXCL12 was decreased by a low dose of nitric oxide, which may in part contribute to the anti-tumor effects observed in our animal study." (PMID 36639681, 2023). "The C-X-C chemokine receptor type 4 (CXCR4), a conserved seven-transmembrane structure spanning the G-protein-coupled receptor, was identified as contributing to tumor metastasis in response to its endogenous ligand stromal cell-derived factor 1 (SDF-1, also named CXCL12)." (PMID 37047831, 2023). "It is determined that CA-MSCs express receptors for VEGF, which not only enhance the migration of MSCs to tumor site but also, with high levels of CXCL12 and deposited fibronectin, increases the migration and adherence of lung carcinoma and melanoma cells to pre-metastatic niche." (PMID 38022534, 2023). "T cell killing assay showed that CXCL12 was able to protect tumor cells from killing by T cells." (PMID 38001512, 2023).
tumor (continued). "CXCL12-activated CRC cells recruit macrophages to the invasive front of the tumor, and they induce their M2 polarization by transferring via exosomes a panel of miRNAs (including miR-25-3p, miR-130b-3p and miR-425-5p) that deplete PTEN transcripts and activate STAT6." (PMID 36831450, 2023). "Interfering with the activity of CXCL12 generated by CAFs enhances T-cell-mediated tumor control." (PMID 36793444, 2023). "In addition to being an essential player in embryogenesis, hematopoiesis, and angiogenesis, CXCL12 displays inflammatory functions in immune surveillance, the inflammatory response, autoimmune diseases, and tumor growth and metastasis." (PMID 37198402, 2023). "Notably, cluster Fib_4 cells exhibited tumor-promoting potential as they overexpressed CXCL12, MMP2, and MMP12." (PMID 37533434, 2023). "OPN-driven CAFs release CXCL12 to initiate EMT in tumor cells." (PMID 37496657, 2023). "Moreover, it seems that in tumor endothelial cells angiogenesis is promoted by the autocrine axis CXCL12/CXCR7 through phosphorylation of the regulated extracellular signal kinase 1/2 (ERK1/2)." (PMID 37445908, 2023). "Furthermore, it has been confirmed that lymph node metastasis can be a source of tumor cells for distant metastases in solid tumors which was related to CXCR4/CXCL12 axis." (PMID 36762192, 2023). "Additionally, cancer-associated fibroblasts (CAFs) actively encourage tumor angiogenesis by producing chemokines and cytokines such as IL-4, IL-8, IL-6, TNF, CXCL12, TGF, and VEGF which have anti-inflammatory and pro-angiogenic properties." (PMID 36829187, 2023). "Since CXCR4 was highly expressed across most T cell subsets in BrM.ICB, the MRC1+LYVE1+ macrophage population could recruit these T cells into the BrM tumor parenchyma through CXCR4:CXCL12 interactions." (PMID 37655659, 2023). "In addition, CXCL12 inhibits the apoptosis of tumor cells, thereby supporting the survival of tumor cells." (PMID 37497001, 2023). "The cancer cells secrete platelet-derived growth factor (PDGF)-D and TGF-β1, both of which activate CAFs, whereas CAFs secrete PDGF-B, heparin-binding EGF-like growth factor (HB-EGF), and stromal cell-derived factor-1 (SDF-1, also known as CXCL12), and thereby promote tumor growth and invasion." (PMID 37174001, 2023). "Notably, the CXCL12/CXCR4 axis holds significant value in cancer studies as it contributes to tumor development as well as the transition of ADMSCs into CAFs." (PMID 38004606, 2023). "In addition, tumor cell infiltration requires a unidirectional transition from migratory to perivascular macrophages, which is regulated by CXCL12 and CXCR4." (PMID 36173487, 2023). "In addition, much lower level of mRNA expressions of CXCL12 which mainly produced by CAFs in the tumor site was observed in the FAP-mBBZ CAR-T group than those from CLDN18.2-mBBZ CAR-T and UTD groups." (PMID 37046312, 2023). "These spots also upregulated the chemokines CXCL9 and CXCL12, which could attract T cells into the tumor via CXCR3 and CXCR4, respectively." (PMID 37655659, 2023). "Chemokines secreted by TAMs, including CCL3, CCL5, CCL15, CCL18, CXCL8 and CXCL12, promote tumor metastasis, angiogenesis, cancer cell survival, immunosuppression and resistance of cancer cells after chemotherapy via CCR1/5, CCR5, CCR1, CCR8, CXCR1/CXCR2, CXCR4, respectively." (PMID 36173487, 2023). "The hypothesis is that inactivation of CXCL12 by NOX-A12 induces changes in the tumor microenvironment of patients with CRC and pancreatic cancer, which would render tumors more susceptible to checkpoint inhibition." (PMID 37372349, 2023). "Four flow rates which could enhance CXCL12 release in vivo depending on the tumor location were used." (PMID 40838055, 2023). "Moreover, since the CXCL12/CXCR4 oncogenic bridge serves as communication between tumor cells and stromal cells, numerous molecules targeting CXCL12/CXCR4 signaling have been developed to interfere with tumor growth." (PMID 36980182, 2023).